ENSG00000286185 (novel protein, identical to neuroblastoma breakpoint family, member 19 NBPF19)
Gene: Protein-coding gene on chromosome 1 (149,390,623 to 149,556,361, forward strand). Ensembl gene ENSG00000286185.
Genetic constraint (gnomAD): Loss-of-function variants: 8 observed, 10.29 expected, observed/expected ratio (o/e) 0.78, 90% interval 0.46 to 1.4. The synonymous counts are far from expectation, so gnomAD's model fits this gene poorly and the ratio says little. Missense variants: 307 observed, 172.5 expected, observed/expected ratio (o/e) 1.78, 90% interval 1.62 to 1.94. Synonymous variants: 112 observed, 67.61 expected, observed/expected ratio (o/e) 1.66, 90% interval 1.42 to 1.91.